CAT (catalase)
Diseases named in the same sentence as CAT in open-access papers (continued):
Sharing a sentence is not in itself a finding about the gene and the disease.
infection (continued). "CAT is another key enzyme which protects living cells by detoxifying H2O2 into water and molecular oxygen near pathogenic infection site." (PMID 33121098, 2020). "Patient-specific airway epithelial cells and differentiated air-liquid interface cultures derived from these were hypersensitive to infection which was at least in part due to oxidative damage since it was partially reversed by catalase." (PMID 30796268, 2019). "In our study, many genes with predicted peroxidase activity (e.g., catalase) were found upregulated during the pathogen Ggt’s infection of wheat roots, a result that agrees with previous reports." (PMID 31338074, 2019). "As previously reported, plant CAT genes played crucial roles in the resistance to pathogen infection." (PMID 30682777, 2019). "In this study, the hepatic GSH level and catalase activity were significantly reduced upon infection, while treatment with IE resulted in the restoration of the GSH level and catalase activity." (PMID 30838089, 2019). "Pre-treatment of A549 cells with catalase prior to D39 infection resulted in diminished IFNβ and IFNa2 transcript levels, in which 5-fold reduction was observed in IFNβ and IFNa2 transcript levels at 5 h post-infection." (PMID 30984149, 2019). "Deletion of the putative secreted catalase‐peroxidase gene in F. graminearum, KatG2, reduced the virulence in wheat spike infection." (PMID 30919582, 2019). "In relation to antioxidants, in general, a lower activity of SOD and CAT enzymes was observed in the liver of the infected animals soon after the infection." (PMID 31653913, 2019). "We also verified that CAT was greatly related to the pathogenicity of Foc TR4 during its infection into banana roots." (PMID 31234790, 2019). "Deletion of OxyR, a key regulator for the response to oxidative stress also in STM, and catalase G leads to attenuation of F. tularensis in the murine infection model." (PMID 31009521, 2019). "As well as, glutathione peroxidase (GSH-PX), superoxide dismutase (SOD), and catalase (CAT) activities in serum samples were measured as a means of assessing the oxidative stress during infection." (PMID 31528024, 2019). "POD activity in alfalfa increased after infection by brownblotch strains, while CAT activity in tobacco increased after infected by pseudomonas solanacearum." (PMID 30616519, 2019). "Further analyses suggest that the accumulation of both catalase-overproducing mutants and rugose colony variants in NAC- mice was the leading cause of mutS mutant enrichment caused by oxidative stress during infection." (PMID 30376582, 2018). "Cells were treated with PEG-catalase 2 h before infection that showed a decrease in ROS secretion, suggesting H2O2 is a significant player in this mode of ROS generation." (PMID 30034380, 2018). "In the Gram-negative pathogen Francisella tularensis, OxyR is required to activate the genes encoding catalase and SOD in response to oxidative stress during infection." (PMID 29891640, 2018). "In the present study, calcium-binding protein, the WD repeat-containing protein, inositol 1,4,5-trisphosphate, endoplasmin-like protein, ubiquitin, and catalase were all found to be up regulated following infection stress." (PMID 30482156, 2018). "The gene expression of the antioxidant enzyme catalase decreased in all treatment groups following infection, with the significant downregulation of catalase occurring in all groups, except the control." (PMID 30237797, 2018). "In Annigeri, no significant expression of SOD and catalase genes was found throughout the infection period except at 12 hpi, where catalase gene was found to be expressed 2-folds than control." (PMID 30158943, 2018). "Lungs samples were harvested at day 1 post-infection to assess mRNA levels of catalase, Cu/Zn-superoxide dismutase (SOD1), CSE, CBS, and 3-MST." (PMID 29740449, 2018).
infection (continued). "CAT activity was markedly increased (p < 0.05) in the E. coli-infected groups at 12 h after infection and then significantly declined (p < 0.05) from 24 h to 72 h in the lean-E." (PMID 30250258, 2018). "As the transcriptome analysis of P. infestans showed the up-regulation of two catalase genes, (PITG_15248 and PITG_07143) during the early infection stages, we then analyzed the expression level of these genes in WT, CK, and transformants." (PMID 28232841, 2017). "A transcriptome analysis of P. infestans has revealed that catalase genes (PITG_15248 and PITG_07143) were up-regulated during early infection stages." (PMID 28232841, 2017). "The level of gene expression for a catalase isoform (CAT3) increases after infection with G. diazotrophicus (2.5-fold), Herbaspirillum rubrisubalbicans (5-fold) and S. scitamineum." (PMID 28222203, 2017). "Acetylcholinestrase (AChE) activities increased during the entire experimental period, whereas those of superoxide dismutase (SOD), peroxidase (POD) and catalase (CAT) decreased during the later infection period." (PMID 28425450, 2017). "If the virus is able to pass this bottleneck, then it establishes a successful cycle of replication, which was seen by the similar infection intensities of the catalase-silenced and control groups of insects." (PMID 28379952, 2017). "The OR of MOB defect predicting subsequent infection with a catalase-positive organism was 33 (p=0.007)." (PMID 26860769, 2017). "Our study, however, reveals that SAH monocytes are characterised by normal phagocytosis with profoundly impaired oxidative burst in a subset of patients who are then demonstrably more likely to contract infection, particularly by catalase-positive organisms." (PMID 26860769, 2017). "The data presented here suggested that catalase silencing altered the so-called midgut infection barrier (MIB) for Dengue-4." (PMID 28379952, 2017). "H2O2 overexpression is induced by pathogen infection in the clam Meretrix meretrix, which then up-regulates CAT to avoid oxidative damage and maintain the effectiveness of the immune system by eliminating excess H2O2." (PMID 29312538, 2017). "A transcriptome analysis of P. infestans revealed that two catalase genes (PITG_15248 and PITG_07143) were up-regulated during early infection stages." (PMID 28232841, 2017). "At 24 hours of infection, there was a significant lower activities of CAT (50.55 ± 6.48, p < 0.01), SOD (3.402 ± 0.57, p < 0.05) and GPx (1.073 ± 0.13, p < 0.01) were observed in GTII bMECs." (PMID 28404882, 2017). "Here, catalase silencing was shown to reduce Dengue-4 prevalence possibly through an alteration in the midgut threshold of infection." (PMID 28379952, 2017). "The GTI infection only at 24 h significantly altered the CAT and GPx activities but the effect was less prominent than GTII." (PMID 28404882, 2017). "HFF cells where infected with the HCMV AD169 strain and, 8 h after infection, were subjected to immunofluorescence analysis with antibodies against vMIA and the peroxisomal marker catalase." (PMID 27181750, 2016). "Infection by downy mildew resulted in markedly enhanced enzyme activities of CAT, APX, G-POD and SOD." (PMID 27065102, 2016). "When chlorantraniliprole was applied in combination with M. anisopliae, SOD and POD activities increased but CAT activities decreased during the initial period post infection." (PMID 27328936, 2016). "In our study, the decreased activities of SOD, POD and CAT suggested a sharp decline in the ability to eliminate ROS during the later phase of infection." (PMID 27328936, 2016). "The methanolic fraction of C. umbellatum prevents the elevated MDA level induced by the infection while significant increase in catalase activity (297.09 to 438.98 %) and glutathione level (58.23 to 95.88 %) were observed after treatment." (PMID 26205948, 2015). "Catalase activity in the liver was increased, while glutathione level in both tissues was decreased after 90 and 120 days of infection." (PMID 25821293, 2015).
infection (continued). "In P. vivax-infected An. aquasalis, catalase and SODexpression was induced 36 h post-infection (p.i.)in the whole mosquitoes." (PMID 25742262, 2015). "The increased CAT activity in the liver was observed at 90 (P=0.03) and 120 (P=0.005) days post-infection." (PMID 25821293, 2015). "During plant response to pathogen infection, SA inhibits the ROS-scavenging enzymes CAT and APX and stabilizes H2O2 levels." (PMID 26172952, 2015). "PbA infection was associated with a significant decrease in brain mRNA levels of the anti-oxidant enzymes SOD-1 and catalase (day 0 vs. day 5)." (PMID 24603727, 2014). "Compared to mice receiving artesunate alone, addition of rosiglitazone adjunctive therapy resulted in significantly increased levels of SOD-1 and catalase expression and full recovery to pre-infection levels by day 9 post-infection." (PMID 24603727, 2014). "Nematode secreted haemoglobins have unusually high affinity for oxygen and possess nitric oxide deoxygenase, and catalase activity thought to be important in protection against host immune responses to infection." (PMID 24009787, 2013). "Catalase is a ROS scavenging enzyme that detoxifies the ROS generated in plants during pathogen infection." (PMID 27234234, 2012). "To distinguish between these possibilities we repeated the infection experiments in the presence of the reductant ascorbic acid or catalase, an enzyme that converts hydrogen peroxide (H2O2) to water and molecular oxygen." (PMID 23028994, 2012). "Fungal-produced catalase was secreted during infection,and appeared to play a role in breaking down the plant-producedH2O2, allowing the disease cycle to occur; in the absenceof catalase, infection was largely blocked by the plant's ROS." (PMID 21533213, 2011). "As the 14028 ΔyqiC::CAT strain grows defectively at physiological temperature, all strains were grown at 28°C prior to infection." (PMID 21554724, 2011). "Three months after AV.RSV.MCAT infection, we examined catalase expression in skeletal muscle and the heart." (PMID 19690612, 2009). "A catalase (catalase B) from Magnaporthe grisea is important for the maintenance of fungal cell-wall integrity during plant cell infection and invasion." (PMID 18927619, 2008). "The strong elevation of CAT protein levels observed after infection with live S. pneumoniae was significantly inhibited by the presence of SB202190." (PMID 18796140, 2008). "Additional genes, that respond to a variety of external stimuli and are often involved in the control of redox balance in the cell, were prevalently downregulated during infection, such as a catalase (TC53791) and a peroxiredoxin Q (TC56223)." (PMID 18366764, 2008). "Significant levels of catalase were produced in NeRCaMs at the third day of AdCat infection compared to mock-infected cells." (PMID 14647150, 2003). "Catalase activity increased in AdCat-infected cells, with different MOIs, starting from the second day after infection as compared to the mock-infected cells (P<0.03)." (PMID 14647150, 2003). "Catalase activity significantly increased at the third day of AdCat infection (with different MOIs) compared to the blank (P<0.03) and to the control (P<0.05)." (PMID 14647150, 2003). "First, Amzn015’s strong antagonism may reduce pathogen-induced oxidative stress, diminishing the need for CAT-mediated detoxification, akin to observations in poplar under milder infection." (PMID 41156759, 2025). "Furthermore, infection decreased CAT activity in the brain exclusively in males, which eliminated the dimorphic pattern observed in uninfected mice." (PMID 40332798, 2025). "No significant changes in CAT activity were observed in the Cd variant, while variants with infection showed a slight (statistically significant in some varieties) increase in this enzyme’s activity." (PMID 41094232, 2025). "At 12 h post-infection, increased CAT and POD activities countered H2O2 overexpression." (PMID 40559070, 2025).
infection (continued). "Hepatic CAT activity post-infection was affected by time and vaccination." (PMID 41256851, 2025). "At 6 h after infection, the CAT activity of the spleen and muscle tissues was 0.27 and 0.85 times higher than that of the control group (P < 0.01), and it kept going down as the infection time went on, but both were still significantly higher than those in the control group (P < 0.01)." (PMID 41401162, 2025). "Intriguingly, SOD activity in the CK group was significantly higher than that in the N. clavispora-infected group, whereas the POD and CAT activities showed an inverse trend, suggesting that pathogen infection suppressed SOD activity while transiently activating the POD and CAT responses." (PMID 41334167, 2025). "The elevated SOD and CAT activity may provide temporary protection against oxidative damage during the acute phase of infection, limiting lipid peroxidation and cellular injury." (PMID 40332548, 2025). "In addition, infection reduced catalase activity in all groups, eliminating the dimorphic patterns described in uninfected mice." (PMID 40332798, 2025). "Similarly, Blumeria graminis can also secrete extracellular catalase to clear H2O2 during infection of barley." (PMID 39254175, 2024). "The melanization response is generally associated with strong catalase activity in insect hemolymph, making it difficult to detect increased ROS during infection without catalase inhibitors." (PMID 38713712, 2024). "By contrast, the infection of Fu13 did not caused changes in CAT activity (p > 0.05), but the inoculation of T891 and the combined application of T891 and Fu13 resulted in significant increases by 45.55 and 69.71%, respectively, when compared to CK (p < 0.05)." (PMID 38572240, 2024). "Insects exhibit dynamic changes in GST and CAT in response to pathogen infection." (PMID 39628478, 2024). "In this study, the supplement of PHB enhanced the expression of SOD and CAT genes in fish blood upon the Vibrio challenge, indicating that Halomonas-PHB can improve the antioxidative capacity of groupers to restore the redox imbalance caused by infection." (PMID 39335239, 2024). "We have previously shown that increased CAT activity is a characteristic feature of wheat plants treated with ET and infected with S. nodorum and is the cause of low H2O2 production in wheat at the early stages of infection." (PMID 39339521, 2024). "The results indicate that following the infection of A. phaeospermum, the levels of defense enzymes (CAT, PPO, POD, SOD, GPX, PAL), chlorophyll, total phenols, and plant hormones in the three transgenic lines (OE-BDUbc, OE-BDSKL1, and OE-BDUbc + BDSKL1) were higher compared to the wild-type plants." (PMID 38203739, 2024). "Furthermore, biochemical and molecular analyses imply that azelaic acid exerts its effects by modulating the ROS pathway, primarily by enhancing catalase enzyme activity leading to a reduced pathogen infection rate." (PMID 39026164, 2024). "In addition, the expression of ROS scavenging enzymes, such as superoxide dismutase (SOD) and catalase (CAT), was also enhanced, mitigating potential oxidative damage induced by pathogen infection." (PMID 38735054, 2024). "Infection with Pt led to elevated CAT activity in both the Morocco and Sakha 94 cultivars." (PMID 39409662, 2024). "In this study, through an investigation into effectors modulating plant ROS levels during the initial infection stages of M. incognita, we discovered a novel effector, CATLe, that exhibits catalase activity and is specifically up‐regulated during the early infection stages." (PMID 39254175, 2024). "Without pathogen infection, CAT-deficient mutants show SA accumulation, induced expression of the SA-pathway marker gene PR1 (pathogenesis-related 1), cell death, along with H2O2 accumulation in tobacco and Arabidopsis." (PMID 36818872, 2023).
infection (continued). "However, the activity of Catalase, Superoxide dismutase, and glutathione peroxidase and the content of Glutathione in the infection group were decreased with the control group (p < 0.01) at a time-dependent manner." (PMID 38155259, 2023). "Vuill., SOD and CAT genes play an essential role in the host infection process of the fungus." (PMID 36975945, 2023). "There was a significant interaction between diet and infection for CAT activity." (PMID 37958062, 2023). "The genes catalase, CuZnSOD, and GST-mu exhibited considerable up-regulation during the later stages of bacterial infection in liver tissue, with Catalase showing increased expression at 72 h post-infection, CuZnSOD at 24 h post-infection, and GST-mu at 7 days post-infection." (PMID 38275638, 2023). "The CAT activity increased by 84.22% (1.0 × 105 spores/mL) and 33.57% (1.0 × 104 spores/mL) at 24 h after infection and decreased by 47.78% (1.0 × 105 spores/mL) and 36.33% (1.0 × 104 spores/mL) at 72 h after infection." (PMID 36835731, 2023). "NpPP2-B10 was induced by salicylic acid, and some resistance-related genes (NtPR1, NtPR2, NtCHN50, and NtPAL) and resistance-related enzymes (catalase and peroxidase) were significantly upregulated in the overexpression lines after infection with P. nicotianae." (PMID 37108517, 2023). "CA metabolism suffered a drastic change upon infection by the quick decline isolate T36, with a reduced profile of secondary metabolites, including flavonoids and polymethoxylated flavonoids, and a low activity of CAT and SOD enzymes." (PMID 36987082, 2023). "Similarly, it has been discovered that the regulation of inducible nitric oxide synthase and CAT expression plays an important role in inflammation management, infection control, and immunological modulation." (PMID 37446564, 2023). "The PCA and heatmap analyses suggested that CAT, APX, SOD, and POD are associated with the tolerance of plants against infection, and a clear positive correlation was also recorded when the non-infected plants were treated with various agents, especially Trichoderma." (PMID 37111917, 2023). "Treatment of infected cells with the H2O2-degrading enzyme catalase prevented Golgi fragmentation, and infection with the H2O2-deficient Spn strain ΔspxB failed to induce Golgi fragmentation, further supporting the involvement of H2O2." (PMID 37592354, 2023). "SOD or CAT are in the first line of defense against excess H2O2 during infection." (PMID 37514180, 2023). "Infection may also lead to a significant increase in the enzymatic activity of liver catalase and superoxide dismutase compared with the normal control group." (PMID 37435530, 2023). "Moreover, pathogens often target CAT to help with infection, which also suggests the importance of photorespiratory H2O2 in immunity." (PMID 36818872, 2023). "Infection with E. tenella or E. acervulina could increase serum CAT activity while it decreases serum GPX activity in broilers." (PMID 35923236, 2022). "Catalase is a well-known antioxidant enzyme produced by fungi as an infection strategy." (PMID 35054864, 2022). "To confirm that photoinactivation of catalase enhances macrophage elimination of intracellular pathogens, we enumerated intracellular bacteria by lysing macrophages with 0.1% Triton X-100 for 3 minutes after 4-hour infection." (PMID 35446788, 2022). "Capnocytophaga canimorsus is a catalase-positive and oxidase-positive gram-negative bacillus commonly found in dog saliva that is a rare cause of infection in immunocompromised individuals." (PMID 35496948, 2022). "Interestingly, we observed the highest level of catalase production in the C. neoformans immediate infection samples (denoted by the smallest zone of inhibition), which did not correspond with the single detectable catalase protein profile." (PMID 35862772, 2022).